ALDH4A1 (aldehyde dehydrogenase 4 family member A1)
Description:
Irreversible conversion of delta-1-pyrroline-5-carboxylate (P5C), derived either from proline or ornithine, to glutamate. This is a necessary step in the pathway interconnecting the urea and tricarboxylic acid cycles. The preferred substrate is glutamic gamma-semialdehyde, other substrates include succinic, glutaric and adipic semialdehydes.
Synonyms: ALDH4; P5CDH; P5CD
Tractability: Small molecule: a structure with a bound ligand is known; it belongs to a druggable protein family. PROTAC: ubiquitination databases record sites on it; its protein half-life has been measured.
Target class: Enzyme; Oxidoreductase
Gene: Protein-coding gene on chromosome 1 (18,871,425 to 18,902,799, reverse strand). Ensembl gene ENSG00000159423.
Subcellular location: Mitochondrion matrix
Subcellular location (Human Protein Atlas): Mitochondria
Pathways (Reactome):
Metabolism: Glyoxylate metabolism and glycine degradation; Proline catabolism
Gene Ontology:
Molecular function: aldehyde dehydrogenase (NAD+) activity; identical protein binding; L-glutamate gamma-semialdehyde dehydrogenase activity; protein binding; oxidoreductase activity; oxidoreductase activity, acting on the CH-NH group of donors, NAD or NADP as acceptor
Biological process: trans-4-hydroxy-L-proline catabolic process; L-proline catabolic process
Cellular component: mitochondrion; mitochondrial matrix
Genetic constraint (gnomAD): Loss-of-function variants: 46 observed, 65.19 expected, observed/expected ratio (o/e) 0.71, 90% interval 0.56 to 0.9. The upper end of that interval is the gene's LOEUF score, 0.9, which puts it in group 3 of 6, group 1 being the genes least tolerant of losing a copy. Missense variants: 748 observed, 744.64 expected, observed/expected ratio (o/e) 1, 90% interval 0.94 to 1.07. Synonymous variants: 323 observed, 316.93 expected, observed/expected ratio (o/e) 1.02, 90% interval 0.93 to 1.12.
Gene-disease validity (ClinGen):
ClinGen rates the evidence that ALDH4A1 causes each of these diseases.
hyperprolinemia type 2 (autosomal recessive): Definitive. Hyperprolinemia type 2 is an autosomal recessive proline metabolism disorder due to pyroline-5-carboxylate dehydrogenase deficiency.
Homologues: Orthologues: chimpanzee ALDH4A1 (99% identical), macaque ALDH4A1 (98% identical), mouse Aldh4a1 (92% identical), guinea pig ALDH4A1 (91% identical), rabbit ALDH4A1 (91% identical), pig ALDH4A1 (90% identical), rat Aldh4a1 (88% identical), dog ALDH4A1 (83% identical), tropical clawed frog aldh4a1 (76% identical), zebrafish aldh4a1 (74% identical), Drosophila melanogaster P5CDh1 (59% identical), Caenorhabditis elegans alh-6 (54% identical), and 1 more. Paralogues in human: ALDH1A2 (25% identical), ALDH2 (25% identical), ALDH1A1 (25% identical), ALDH1B1 (25% identical), ALDH1A3 (25% identical), ALDH1L2 (25% identical), ALDH9A1 (24% identical), ALDH1L1 (24% identical), ALDH8A1 (23% identical), ALDH5A1 (21% identical), ALDH16A1 (20% identical), ALDH6A1 (19% identical), and 5 more.
Diseases named in the same sentence as ALDH4A1 in open-access papers:
ALDH4A1 is named in the same sentence as 40 diseases in open-access papers, as found by Europe PMC text mining. Sharing a sentence is not in itself a finding about the gene and the disease. The quoted sentences say what the papers report.
hyperprolinemia type 2 (9 papers, 2015 to 2026). "Hyperprolinemia type II (HPII) is an inborn error of metabolism due to genetic variants in ALDH4A1, leading to a deficiency in Δ-1-pyrroline-5-carboxylate (P5C) dehydrogenase." (PMID 36131087, 2022). "We describe two novel ALDH4A1-variants in an adult patient with hyperprolinemia type II causing secondary pyridoxine deficiency and seizures." (PMID 31884946, 2019). "A deficiency in P5CDh, which is encoded by the ALDH4A1 gene, leads to hyperprolinemia type II (HPII)." (PMID 40710547, 2025). "Mutation in proline dehydrogenase (PRODH) in humans results in hyperprolinemia type I (HPI), while mutation in delta-1-pyrroline-5-carboxylate dehydrogenase (ALDH4A1/P5CDH) results in hyperprolinemia type II (HPII)." (PMID 32022684, 2020). "No pathogenic variants were detected in ALDH4A1, which encodes P5C dehydrogenase (EC 1.2.1.88) (data not shown), defects of which cause hyperprolinemia type II." (PMID 34285201, 2021). "Hyperprolinemia type 2 (HPII) is a rare autosomal recessive disorder of the proline metabolism, that affects the ALDH4A1 gene." (PMID 31884946, 2019).
hyperprolinemia (7 papers, 2013 to 2021). Hyperprolinemia is when there isan excess of a particular protein building block (amino acid), called proline, in the blood. "ALDH4A1 deficiency leads to hyperprolinemia; patients present with epilepsy and intellectual disability." (PMID 34532350, 2021). "Deletion of both copies through exons 6 to 10 of the ALDH4A1 gene in patient 15 likely caused the genetic disorder, hyperprolinemia (OMIM 942510)." (PMID 28851938, 2017). "It has been reported that mutation of the P5Cdh ortholog ALDH4A1 in humans causes the genetic disease type II hyperprolinemia, which is characterized by elevating levels of P5C, resulting in mental retardation and convulsions." (PMID 24039956, 2013).
atherosclerosis (6 papers, 2021 to 2025). A disease characterized by the build-up of fatty material and calcium deposition in the arterial wall resulting in partial or complete occlusion of the arterial lumen. "ALDH4A1 is significantly elevated in the plasma of atherosclerosis-prone mice and atherosclerotic human tissue, and anti-ALDH4A1 antibodies have potential therapeutic value in cardiovascular disease." (PMID 40738191, 2025). "A recent study discovers that circulating ALDH4A1 is significantly elevated in the plasma of mice and humans with atherosclerosis, and the administration of ALDH4A1 antibody can protect against atherosclerosis progression." (PMID 36694633, 2023). "ALDH4A1 can serve as a potential disease indicator, in which circulating ALDH4A1 is increased during atherosclerosis in mice and humans and anti‐ALDH4A1 antibodies can protect against atherosclerosis progression." (PMID 36694633, 2023). "ALDH4A1 reduced the free cholesterol and low density lipoprotein (LDL) to improve atherosclerosis progression by involving in proline metabolism." (PMID 35126115, 2021). "In addition, the yeast two-hybrid assay indicated that desmin’s head domain also interacts with aldehyde dehydrogenase 4 family member A1 (ALDH4A1) (clone-132), which is a mitochondrial enzyme involved in proline metabolism and is related to atherosclerosis." (PMID 38607042, 2024).
ovarian carcinoma (3 papers, 2021 to 2024). A malignant neoplasm originating from the surface ovarian epithelium. "Aldehyde dehydrogenases (ALDH4A1 and ALDH6A1) overexpression has been shown to be associated with poorer overall patient survival, particularly in breast, head and neck, cervical and ovarian cancers." (PMID 39403185, 2024).
prostate carcinoma (3 papers, 2023 to 2025). A carcinoma that arises from epithelial cells of the prostate gland. "Although ALDH1A1 and ALDH3A1 are most often associated with cancer stem cells, high ALDH4A1 expression has been reported in prostate cancer cells and primary cultures of human prostate cancer." (PMID 39598797, 2024). "By analyzing six primary prostate cancer specimens and eight prostate cancer cell lines, it was indicated that ALDH isoforms with higher expression levels were ALDH3A2, ALDH4A1, ALDH7A1, ALDH9A1, and ALDH18A1." (PMID 37686694, 2023). "Furthermore, it has been demonstrated that ALDH4A1 and ALDH9A1 are the primary enzyme isoforms responsible for ALDEFLUOR activity in prostate cancer tissues, whereas ALDH3A2 and ALDH18A1 are the predominant enzyme isoforms in non-tumor tissues and high-grade prostate intraepithelial neoplasia." (PMID 37686694, 2023).
schizophrenia (3 papers, 2021 to 2024). A major psychotic disorder characterized by abnormalities in the perception or expression of reality. "In addition, patients with ALDH4A1 gene deficiency suffer from schizoaffective disorders and schizophrenia, and the potential molecular mechanism is also associated with abnormal proline metabolism." (PMID 36694633, 2023). "The expression levels of two degradation enzymes, ALDH4A1 and PRODH, were lower in the brains of schizophrenia patients when compared to healthy controls." (PMID 37815900, 2024).
colorectal cancer (2 papers, 2020 to 2022). A primary or metastatic malignant neoplasm that affects the colon or rectum. "The function of ACAT1, ALDH4A1, and FAS in colorectal cancer has been verified by previous studies, participating in the progression of CRC." (PMID 35992263, 2022).
lung carcinoma (2 papers, 2020 to 2022). "ALDH4A1 is downregulated in lung cancer and is an important biomarker for differentiating lung cancer tumor tissue from normal tissue." (PMID 36177002, 2022).
Cirrhosis (1 paper, 2015). A chronic disorder of the liver in which liver tissue becomes scarred and is partially replaced by regenerative nodules and fibrotic tissue resulting in loss of liver function. "The ALDH4A1 mRNA is up-regulated in late HCV cirrhosis and HBV pathogenesis." (PMID 25707620, 2015).
co-infection (1 paper, 2025). "Regarding the co-infection of cells by E. coli and S. aureus, the unique genes of ES2 are DZIP1 and SMTNL2; the unique genes of ES3 are ALDH4A1, DNASE1L1, FAM227A, and KAT2B; and ES1 has 143 unique genes." (PMID 40771952, 2025).
diabetes (1 paper, 2022). "Except for the completely restored DEGs, Sal treatment mitigated the expression of approximately 73.08% up-regulated DEGs and 66.35% down-regulated DEGs induced by diabetes, including 8 oxidation-related genes (Aldh4a1, Acad12, Ado, Kdm4d, Acacb, Mical1, Th and Htatip2)." (PMID 35370972, 2022).
Insulin resistance (1 paper, 2019). Increased resistance towards insulin, that is, diminished effectiveness of insulin in reducing blood glucose levels. "Prostate androgen-regulated mucin-like protein 1 (PARM1), ALDH4A1, VENTX, and KIAA0040 are novel biomarkers for the development of insulin resistance." (PMID 30678306, 2019).
male infertility (1 paper, 2021). The inability of the male to effect fertilization of an ovum after a specified period of unprotected intercourse. "If conserved, Aldh4a1 may act as a potential genetic biomarker in the diagnosis and treatment of male infertility." (PMID 33480139, 2021).
neuroblastoma (1 paper, 2015). Neuroblastoma (NB) is the most common solid, extracranial childhood tumor. "Kaplan-Meier analysis showed that low levels of ALDH4A1 mRNA expression in human neuroblastoma tissues positively correlated with poor patient prognoses (p ¡ 0.01)." (PMID 25707620, 2015). "As low levels of miR-184 in human neuroblastoma tissues also correlates with poor patient survival, the data suggest that miR-184 is likely to positively regulate ALDH4A1 expression in tumours." (PMID 25707620, 2015).
Obesity (1 paper, 2018). Accumulation of substantial excess body fat. "The top predictors, rs10521308 (FTO), rs2206135 (CTNNBL1), cg13438334 (DGAT1), and cg22390041 (ALDH4A1) are located in genes known to be associated with obesity risk." (PMID 30255820, 2018).
pulmonary fibrosis (1 paper, 2021). Chronic progressive interstitial lung disorder characterized by the replacement of the lung tissue by connective tissue, leading to progressive dyspnea, respiratory failure, or right heart failure. "Therefore, we speculated that mesenchymal ALDH1a1 and ALDH4a1 might protect against BLM-induced pulmonary fibrosis." (PMID 34425896, 2021).
thyroid cancer (1 paper, 2025). "Similarly, ALDH1A1, alongside other aldehyde dehydrogenase family members such as ALDH4A1 and ALDH3A2, underscores the role of metabolic dysregulation in thyroid cancer progression." (PMID 40861812, 2025).
tumor (8 papers, 2015 to 2025). "Variants in ALDH4A1 may modify the cellular response to oxidative stress in tumor environments, affecting growth rates and resistance to therapies." (PMID 40104216, 2025). "Up-regulation of ROCK1 and TPR and down-regulation of ALDH4A1 and CLCA2 are positively associated with the processes of migration, metastasis, and invasion of tumor cells and negatively associated with proliferation." (PMID 31438847, 2019). "Exome sequencing identified unique variants in AA patient samples within key genes, including TP73 (tumor suppression), XYLB (metabolism), ALDH4A1 (oxidative stress), PTPRB (cellular signaling), and HLA-DRB5 (immune response)." (PMID 40104216, 2025). "Both low and high proliferative luminal tumours showed weak positive correlation between GLS2 protein and ALDH18A1 (p < 0.001), ALDH4A1 (p < 0.01), ATF4 (p = 0.001), PRODH (p < 0.001), SLC38A2 (p ≤ 0.001) and SLC7A11 (p < 0.001)." (PMID 34439127, 2021). "Some tumor type-specific DEs were observed for ALDH1L1, ALDH3B1, ALDH3B2, ALDH4A1 and ALDH7A1." (PMID 29426835, 2018).
cancer (5 papers, 2021 to 2025). A tumor composed of atypical neoplastic, often pleomorphic cells that invade other tissues. "The results of immunohistochemistry (IHC) in the Human Protein Atlas (HPA) database showed that compared with normal tissues, ENOPH1, ACAT1, ALDH4A1, FAS, and ASPG are downregulated in cancer tissue than in normal tissue." (PMID 35992263, 2022).
metabolic disorder (5 papers, 2015 to 2024). "Polymorphisms in ALDH4A1 are associated with metabolic diseases, mainly characterized by neurological manifestations." (PMID 39766878, 2024). "Pathogenic variants in the ALDH4A1 gene cause HPII, a metabolic disorder of the proline degradation pathway that can result in retardation and convulsion." (PMID 36694633, 2023).
ALDH4A1 also shares sentences with these, for which no sentence is quoted: infection (5 papers); breast carcinoma (4); autism spectrum disorder (2); Intellectual disability (2); pyridoxine-dependent epilepsy (2); schizoaffective disorder (2); Alzheimer disease (1); cardiovascular disease (1); colon cancer (1); developmental delay (1); epilepsy (1); female sterility (1); genetic disorder (1); Hyperammonemia (1); hyperprolinemia type 1 (1); Kabuki syndrome 2 (1); Methylmalonic aciduria (1); panic disorder (1); Sjögren-Larsson syndrome (1); viral infection (1).